VWF (von Willebrand factor)
Diseases named in the same sentence as VWF in open-access papers (continued):
Sharing a sentence is not in itself a finding about the gene and the disease.
thrombosis (continued). "Likewise, VWF replacement in acute bleeding other than in VWF deficiencies is not clinically established due to association with a high risk of venous thrombosis." (PMID 37647278, 2023). "Interestingly, we found a correlation between VWF and the JAK2V617F allele burden and thrombosis." (PMID 35626232, 2022). "In addition, the reduced levels of ADAMTS-13, which is responsible for cleaving VWF into smaller and less active molecules, in the thrombosis group supports the implication of VWF and ADAMTS-13 in the pathogenesis of the typical SARS-CoV-2 prothrombotic phenotype." (PMID 35482749, 2022). "The exact level of VWF inhibition needed to prevent arterial thrombosis is unknown." (PMID 32636459, 2020). "Similarly, in a study of older British men with no prevalent arterial or venous thrombosis D-dimer and vWF were significantly associated with NT-proBNP." (PMID 31234593, 2019). "Finally, investigating whether the erythrocyte-VWF interactions could play a role in hemostasis and (venous) thrombosis and exploring ways to modulate these interactions will likely prove to be of clinical relevance." (PMID 28249049, 2017). "Repeated infusions of pd-VWF/FVIII for severe bleedings or major surgery may result in a significant accumulation of FVIII, that is exogenously infused and endogenously synthesized and stabilized by the infused VWF, with possible occurrence of deep vein thrombosis or cardiovascular problems." (PMID 28394285, 2017). "According to De Meyer and co-workers in 2011, the importance of GPIbα far exceeds that of VWF in arterial thrombosis and GPIbα is a central receptor in different vascular processes of thrombosis and inflammation, all of which may contribute to the progression of ischemic stroke." (PMID 27036108, 2016). "Later on, more physiologically relevant models of deep vein thrombosis (DVT) proved essential to further understand the role of platelets and VWF/GPIbα interaction in DVT." (PMID 25297919, 2015). "Besides, among the fifteen novel SNPs showing promising association at p < 10-5 with either vWF or FVIII levels in the meta-analysis, one located in ACCN1 gene also showed weak association (P = 0.0056) with venous thrombosis in a sample of 1,946 cases and 1,228 controls." (PMID 21810271, 2011). "The concomitant elevation of both hemostatic (FVIII, vWF) and inflammatory (fibrinogen, CRP) markers observed in patients with a SYNTAX score ≥33 suggests a complex interplay between thrombosis and inflammation in atherosclerotic disease." (PMID 41007843, 2025). "Remarkably, elevated vWF: Ag levels were significantly associated with both venous and arterial events, even when analyzed separately; patients with VTEs showed higher vWF: Ag levels as compared to patients with ATEs, which in turn had higher levels as compared to patients without thrombosis." (PMID 41085687, 2025). "Total VWF and VWF pro-peptide levels were significantly higher in APS, thrombosis controls and AID patients compared to normal controls, indicating that more VWF is released from the vessel wall and VWF is unfolded more frequently." (PMID 39726607, 2024). "In the studied cohort, unfolded VWF was increased in APS, thrombosis and AID patients, confirming previous findings of Hulstein and al." (PMID 39726607, 2024). "For unfolded VWF, 46% of APS patients, 36% of thrombosis patients, and 29% of AID patients were above the cut-off value." (PMID 39726607, 2024). "For total VWF, 33% of APS patients, 36% of thrombosis patients, and 20% of AID patients were above the cut-off value." (PMID 39726607, 2024). "Lastly, 39% of APS patients, 41% of thrombosis patients, and 41% of AID patients were above the cut-off value for VWF pro-peptide." (PMID 39726607, 2024). "Unfolded VWF levels were significantly higher in APS (+53%), thrombosis (+50%), and AID patients (+36%)." (PMID 39726607, 2024).
thrombosis (continued). "Total VWF levels were significantly higher in APS patients, thrombosis patients and AID patients compared to normal controls (+41%, +49% and +31%, respectively)." (PMID 39726607, 2024). "Our results suggest that indeed VWF is a biomarker for not only APS, but also auto-immune diseases and thrombosis in general." (PMID 39726607, 2024). "Higher levels of fibrinogen and vWF can lead to intravascular thrombosis, vascular damage, and thrombotic complications, whereas lower levels of ADAMTS13 result in decreased cleavage of large prothrombotic vWF multimers." (PMID 34559294, 2022). "Considering that the active coagulation process in patients with PVT may alter the circulating vWF:Ag levels in plasma; we performed a stratified analysis based on whether patients had PVT or not and found that vWF:Ag could distinguish the high-risk patients well regardless of thrombosis." (PMID 35360443, 2022). "We reported that patients with thrombosis have AECA-mediated endothelial activation marked by the expression of adhesion molecules such as ELAM-1, ICAM-1, and VWF." (PMID 35626232, 2022). "NETs can also recruit red blood cells, promote von Willebrand Factor (VWF), fibrinogen and fibrin deposition, thereby inducing venous thrombosis." (PMID 33816356, 2021). "aTTP is a blood disorder in which the activity of von Willebrand factor (vWf)-cleaving protease ADAMTS-13 is highly inhibited, which leads to the formation of vWf-platelet aggregates and microvascular thrombosis." (PMID 34576851, 2021). "The study also focused on VWF and F8 due to the strong role of the respective encoded proteins in the maintenance of hemostasis and thrombosis equilibrium and because increased VWF and FVIII levels have been already described as associated with an increased DVT risk." (PMID 34662354, 2021). "Our study has fully proved that flow disturbance accelerates the FeCl3-induced thrombosis and the effects are dependent on the VAMP3 and SNAP23-mediated VWF secretion." (PMID 33224946, 2020). "In the framework of the ongoing prospective Cancer and Thrombosis Study (CATS) ADAMTS‐13 activity and VWF antigen levels were investigated in cancer patients." (PMID 31294335, 2019). "Our results revealed that TF, FVIII, and FIX, but not VWF, correlated with cancer cell-derived MV-induced thrombosis." (PMID 40217494, 2025). "For VWF to contribute to venous thrombosis in the absence of overt endothelial damage, it seems highly likely that platelet capture is mediated by the formation of VWF strings/cables that can ensue following VWF release." (PMID 39908367, 2025). "Preoperative VWF activity was higher in children with CHD who developed thrombosis after surgery compared to those without thrombosis (SMD: 0.58, 95% CI: 0.20–0.96), with a random-effects model used." (PMID 39896721, 2025). "The role of VWF in venous thrombosis is perhaps less obvious given the lack of vessel damage and the low shear environment." (PMID 39908367, 2025). "The binding of platelets to VWF strings over the endothelial surface under venous flow alone does not represent thrombosis." (PMID 39908367, 2025). "Our analysis found that preoperative VWF activity was higher in children who developed thrombosis after surgery compared to those without thrombosis (SMD: 0.58, 95% CI: 0.20–0.96)." (PMID 39896721, 2025). "Interestingly, multiple injections of recombinant factor VIII failed to induce thrombosis in VWF-deficient mice, suggesting that impaired coagulation was not the primary reason for the absence of DVT in these animals." (PMID 40299499, 2025). "As the VWF aptamer inhibits platelet recruitment and activation, PAI-1 levels may be reduced in thrombosis in the aptamer-treated canines, which may, in part, result in improved recanalization rates in arterial platelet-rich clots with AIS." (PMID 39445200, 2024).
thrombosis (continued). "Together with our results, these findings suggest that vWF/FBLN-5 disorder-induced thrombosis and vascular injury may be interrelated, or rather, thrombosis and vascular damage occur together." (PMID 38649864, 2024). "In the current study, we found a remarkable difference in ORs for the association of high unfolded VWF levels and APS compared to non-APS thrombosis patients and non-APS AID patients." (PMID 39726607, 2024). "Similarly, VWF pro-peptide levels were higher in APS (+27%), thrombosis (+36%), and AID patients (+26%)." (PMID 39726607, 2024). "The vWF activity in patients with venous thrombosis was significantly higher than that in patients without venous thrombosis (P < 0.01)." (PMID 37442989, 2023). "NAC can act on ROS to reduce oxidative stress and restore the endothelium from endotheliitis, thereby reducing the amount of vWF released from the sub-endothelium that inhibits platelet activation and NET formation and ultimately prevents vascular thrombosis and COVID-19 infection and severity." (PMID 37534078, 2023). "α2M was significantly lower in the thrombosis group, and FVIII and VWF were significantly higher." (PMID 36248875, 2022). "However, in mouse models for venous thrombosis based on the (partial) ligation of the inferior vena cava (IVC), VWF−/− mice were protected from the disease." (PMID 36361963, 2022). "Although the effects imposed by surgery were described, the levels of VWF and ADAMTS13 may change more dramatically or in an unexpected manner in overt thrombosis." (PMID 36362664, 2022). "Statistically significant higher levels of VWF at admission were found in patients who developed thrombosis (group 1) than those who did not (group 2); it was an independent predictor of later thrombosis." (PMID 35061142, 2022). "The VWF:Ag levels were significantly elevated in the patients with thrombosis (75 ± 10 ng/mL) and normal in those without thrombosis (25 ± 2 ng/mL) and the controls (18 ± 2 ng/mL)." (PMID 35626232, 2022). "We found high ELAM-1 and ICAM-1 as well as high VWF:Ag in patients with thrombosis compared to patients without thrombosis." (PMID 35626232, 2022). "Markers such as D-dimer, high levels of fibrinogen, factor VIII, and von Willebrand factor have a primary role in diagnosing and mortality prognosis of different venous thromboembolism (VTE) disease phenotypes, including asymptomatic deep vein thrombosis (DVT) in coronavirus disease 2019 (COVID-19)." (PMID 35936165, 2022). "Multimers of vWF, released from activated endothelium, were recorded as spontaneously recruiting excessive circulating platelets and PMN, thereby promoting intravascular thrombosis, which is commonly observed in severe cases of canine angiostrongylosis." (PMID 34065858, 2021). "For example, von Willebrand factor mutant mice, which support human but not murine platelet-induced thrombosis, have been used to study the P2Y12 receptor antagonist clopidogrel in vivo." (PMID 33123018, 2020). "Although it is frequently implied that VWF is only important for platelet capture under high shear conditions, murine models of venous thrombosis with no collagen exposure have repeatedly revealed an important role for VWF-mediated platelet accumulation." (PMID 32314961, 2020). "VWF antigen/ADAMTS13 ratio has a significant prognostic power at different time points after heart attacks concomitant with higher chances of adverse outcomes in clinical practise, like heart failure and thrombosis." (PMID 32095288, 2020). "The wide distribution of vWF in our patient groups does not support the use of this marker as a clinical predictor for recurrent thrombosis in HIV patients." (PMID 25814984, 2015). "Mice lacking VWF were the first genetically engineered mice evaluated using an in vivo thrombosis model performed in mesenteric arterioles and visualized through intravital microscopy." (PMID 25297919, 2015).
thrombosis (continued). "Results showed that some HP strains are able to bind to the von Willebrand factor to interact with glycoprotein Ib and to induce platelet aggregation in humans and HP may eventually affect IHD by eliciting thrombosis." (PMID 24574896, 2014). "Tirado and colleagues analyzed 250 patients with venous thrombosis and 250 unrelated controls and found higher VWF levels in non-O group, which was more frequent in patients." (PMID 17894864, 2007). "We performed multinomial logistic regression to investigate whether the high levels of total VWF, unfolded VWF and/or VWF pro-peptide above the cut-off value are associated with APS, non-APS thrombosis and/or non-APS AID." (PMID 39726607, 2024). "Unfolded VWF levels above the 90th percentile in normal controls were associated with an odds of APS (OR: 8.51; CI:3.26 - 22.2; p<0.001), compared to ORs of non-APS thrombosis (OR:5.87; CI:2.07 - 16.7, p=0.001) and AID (OR:3.71; CI:1.40 – 9.87; p=0.009)." (PMID 39726607, 2024). "In this study, we investigated whether high plasma levels of unfolded VWF are associated with thrombotic APS, non-APS thrombosis and non-APS auto-immune diseases (AID)." (PMID 39726607, 2024). "Furthermore, we investigated whether subjects with two or three VWF levels above the 90th percentile of control subjects have higher odds of having APS, thrombosis or AID." (PMID 39726607, 2024). "vWF exhibits a prothrombotic effect by carrying FVIII and facilitating platelet aggregation and adhesion; indeed, patients with thrombotic complications such as deep vein thrombosis, ischemic stroke, and myocardial infarction have increased levels of circulating active vWF." (PMID 39201390, 2024). "For instance, individuals with high basal levels of VWF, when aged and/or have comorbidities, if infected with CoV-2 may reach a VWF threshold that leads to the development of thrombosis, while people with low basal levels of VWF may not." (PMID 34575297, 2021). "Akin to these observations, a non-linear platelet binding to von-Willebrand factor is observed in thrombocytosis, and it is also known that patients with essential thrombocythaemia do not necessarily exhibit higher risks of thrombosis with increasing platelet counts per se." (PMID 31360453, 2019). "Interestingly, this thrombosis defect is not due to abnormal VWF–GPIb adhesive function, nor defective platelet activation induced by soluble platelet agonists, but rather, through reduced platelet PS exposure and procoagulant function." (PMID 27670677, 2016). "Interestingly, this thrombosis defect is not related to alterations in von Willebrand factor (VWF)–GPIb adhesive function or platelet activation, but instead associated with reduced platelet phosphatidylserine (PS) exposure and procoagulant function." (PMID 27670677, 2016). "Thus, it appears that GPIbα contributes to arterial thrombosis by adhesion mechanisms dependent and independent of VWF." (PMID 25297919, 2015). "Additionally, a colocalization network comprising fibrinogen, extracellular DNA, and vWF is observed within a thrombus, which has implications for various inflammatory and thrombotic diseases, including AIS and deep vein thrombosis (DVT)." (PMID 38654328, 2024). "It is not clear whether increased levels of vWF trigger blood clotting and thrombosis in vein grafts; however, in the clinical setting, anticoagulation therapy takes place in the presence of inflammation in order to prevent deep vein thrombosis." (PMID 35743073, 2022). "Furthermore, the expression of circulating markers as von Willebrand factor, VCAM-1 and soluble p-selectin have been found to be higher in patients with atherosclerotic lesions and venous thrombosis, suggesting inflammation as the cause and not the consequence of thrombosis." (PMID 39851572, 2025). "Consequently, increased VWF may be related to inflammation markers without presence of thrombosis." (PMID 40557182, 2025).
thrombosis (continued). "(Unfolded) VWF levels were studied in normal controls (n=93), APS patients (n=64), non-APS thrombosis patients (n=39) and non-APS auto-immune disease (AID) patients (n=49." (PMID 39726607, 2024). "We measured the levels of total VWF, unfolded VWF and VWF pro-peptide in a cohort of 93 normal controls, 54 thrombotic APS patients, 39 non-APS thrombosis patients and 49 non-APS AID patients." (PMID 39726607, 2024). "After adjustment for age and sex, high total VWF gave an OR of 3.82 (CI: CI: 1.44-11.3, p<0.001) for APS, an OR of 4.65 (CI: 1.64-13.2, p<0.001) for non-APS thrombosis." (PMID 39726607, 2024). "Among the MPN patients, the VWF and FVIII:C levels were significantly higher in the patients with SVT than those without thrombosis (p = 0.007 and p = 0.04, respectively)." (PMID 38672756, 2024). "Unfolded VWF levels were respectively, 53%, 50% and 36% higher in APS patients, non-APS thrombosis patients and AID patients, compared to normal controls (p<0.0001)." (PMID 39726607, 2024). "We also found increases in some but not all markers of thrombosis in those with severe disease including elevated PAI-1 and vWF activity." (PMID 37026003, 2023). "Furthermore, recent studies are suggesting hemostatic factors, including the Von Willebrand Factor (VWF), in the development, progression, and resolution of deep vein thrombosis (DVT), including UEDVT, which can include novels aspects to consider in the management of this condition." (PMID 37460994, 2023). "A global assay of all hemostatic parameters including D-dimer, von Willebrand factor (vWF) antigen, factor VIII levels, lupus anticoagulant, antithrombin III, etc. and ultrasonography to assess for thrombosis was not done in our study." (PMID 34877233, 2021). "We collected samples from patients with and without thrombosis and compared plasma levels of lipopolysaccharide (LPS), LPS binding protein (LBP), soluble CD14 (sCD14), and von Willebrand Factor antigen level (vWF)." (PMID 25814984, 2015). "Humate-P is a human plasma-derived vWF/FVIII concentrate with an extensive, three-decade track record of no thrombosis and no cases of viral transmission." (PMID 26113995, 2015). "Fourth, although we included many outpatients with LC, this study excluded those with the presence of occult thrombosis-provoking factors, those in whom CECT could not be performed, and those in whom ADAMTS13:AC and VWF:Ag could be affected." (PMID 38473925, 2024). "In the crude model, total VWF values above the 90th percentile cut-off resulted in an odds ratio (OR) of 4.67 (CI: 1.92-11.3, p<0.001) for APS, and an OR of 5.23 (CI: 2.02-13.5, p<0.001) for non-APS thrombosis." (PMID 39726607, 2024).